RN7SKP246 (RN7SK pseudogene 246)
Gene: Miscellaneous RNA gene on chromosome 5 (144,535,354 to 144,535,670, reverse strand). Ensembl gene ENSG00000201423.
Homologues: Orthologues: chimpanzee 7SK (96% identical). Paralogues in human: 7SK (78% identical), RN7SKP176 (77% identical), RN7SKP255 (75% identical), RN7SKP180 (74% identical), RN7SKP187 (74% identical), RN7SKP80 (74% identical), RN7SKP189 (74% identical), RN7SKP71 (74% identical), RN7SKP78 (74% identical), RN7SKP9 (73% identical), RN7SKP243 (73% identical), RN7SKP37 (73% identical), and 284 more.